EPOR (erythropoietin receptor)
Diseases named in the same sentence as EPOR in open-access papers (continued):
Sharing a sentence is not in itself a finding about the gene and the disease.
neuroblastoma (6 papers, 2007 to 2018). Neuroblastoma (NB) is the most common solid, extracranial childhood tumor. "For example, undifferentiated human neuroblastoma cells express EpoR and Epo treatment prevents augmented apoptosis following the exposure to pro-apoptotic stimuli." (PMID 29393890, 2018). "In another study, EpoR expression in neuroblastoma primary tumors has been shown to have significantly lower expression when compared to paired lymph node metastases, a further indication that EpoR is highly implicated in metastasis." (PMID 22188703, 2011). "Differentiated neuroblastoma cell line SHSY-5Y was reported to express extremely low (∼17) EpoR homodimers on the cell surface." (PMID 18349818, 2008). "Upon differentiation into neuron-like cells (induced by treatment of neuroblastoma cells with all-trans-retinoic acid) EpoR was downregulated and Epo no longer had an anti-apoptotic effect." (PMID 29393890, 2018). "Although EPOR expression on tumor cells is typically several orders of magnitude lower than on erythroid progenitor cells, EPO can still activate cell signaling cascades in tumor cells, such as in differentiated neuroblastoma SH-SY5Y cells, which have fewer than 50 EPOR dimers on their cell surface." (PMID 28418910, 2017). "In a study suggesting that neuroblastoma SH-SY5Y cells contain EpoR molecules (<50 receptors per cell surface) that transmit an anti-apoptotic signal when exposed to an ESA, cell surface EpoR could not be reliably detected using a radioactive Epo-binding assay." (PMID 22395661, 2012).
non-small cell lung carcinoma (6 papers, 2011 to 2020). A group of at least three distinct histological types of lung cancer, including non-small cell squamous cell carcinoma, adenocarcinoma, and large cell carcinoma. "Because the clinical significance of erythropoietin receptor (EPOR) signaling in human non-small cell lung cancer (NSCLC) also remains controversial, our aim was to study whether EPO treatment modifies tumor growth and if EPOR expression has an impact on the clinical behavior of this malignancy." (PMID 24155958, 2013). "Functional significance of co-expressed erythropoietin (EPO) and its receptor (EPOR) in non-small cell lung cancer (NSCLC) had been under debate." (PMID 29137269, 2017). "Furthermore, since the EpoR is also expressed on some tumor cells such as non-small cell lung carcinoma cell lines, it of much interest to investigate to which degree principles learned in suspension cells can be transferred to adherent cancer cells." (PMID 28945754, 2017).
Glucose intolerance (5 papers, 2013 to 2025). Glucose intolerance (GI) can be defined as dysglycemia that comprises both prediabetes and diabetes. "EPOR(nestinKO) mice show greater high fat-diet induced weight gain and glucose intolerance, particularly in male mice." (PMID 34603036, 2021). "Given that EPO has been used in humans, EPO or new EPOR agonists may be valuable for the intervention of glucose intolerance-related metabolic syndrome and T2D." (PMID 23326455, 2013).
polycythemia vera (5 papers, 2009 to 2024). "Within the group of primary erythrocytosis, erythropoietin receptor (EPOR) mutation (congenital) and polycythemia vera (PV, acquired) stand out." (PMID 24363938, 2013). "Jak2 mediates EpoR signaling and is a causal gene of polycythemia vera." (PMID 33481887, 2021).
renal carcinoma (5 papers, 2008 to 2021). A carcinoma arising from the epithelium of the renal parenchyma or the renal pelvis. "Epo and EpoR co-expressed in primary renal cancer cells and 6 human RCC cell lines." (PMID 23028796, 2012). "EpoR and its signaling molecules STAT5, Akt, and Erk1/2 were constitutively activated in primary renal cancer cells, 786-0 cells and Caki-1 cells." (PMID 23028796, 2012). "In this study, we used cultured human primary renal cancer cells and RCC cell lines including 786-0 (VHL-mutant) and Caki-1(VHL-normal) to study the role of Epo/EpoR pathway on cell proliferation, apoptosis, invasiveness, and sensitivity to anti-tumor drug Sunitinib in RCC cells." (PMID 23028796, 2012).
Sepsis (5 papers, 2012 to 2022). Sepsis is defined as life-threatening organ dysfunction caused by a dysregulated host response to infection. "Third, sepsis can interrupt the iron steady state, trigger bone marrow suppression, and downregulate the expression of the erythropoietin receptor, which all contribute and cause more production of ineffective red blood cell and RDW increased." (PMID 35227247, 2022). "Because of the pleiotropic effects of EPO, increased EPO production during sepsis is not only due to renal hypoxia but possibly also a response toward EPOR reduction." (PMID 34831360, 2021). "Because EPO protects several organs, including the liver, through activation of the EPO receptor/β-common receptor (EPOR/βcR) complex, the inadequate expression of EPOR during sepsis possibly reduced the protective effects of EPO." (PMID 34831360, 2021). "An increased dose of EPO is necessary to maintain hematocrit (Hct) during septicemia, perhaps due to sepsis-reduced EPOR." (PMID 34831360, 2021). "Although the relationship between TLR4 and NF-κB activation remains hypothetical, we found indirect evidence that EpoR activation plays a role in sepsis-mediated inflammation." (PMID 22235348, 2012). "We also found that renal EpoR expression, which was downregulated in this model of sepsis, was preserved by pretreatment with CERA." (PMID 22235348, 2012). "The contrasting EPOR longitudinal profiles between severe and mild patients in our cohort are likely to reflect the changes in erythropoietin responsiveness that accompany critical illness and sepsis in ESKD patients." (PMID 36522333, 2022). "Hence, the increased EPO production in sepsis is, partly, a compensation for the reduced EPOR in sepsis and implies a possible influence of EPO on sepsis." (PMID 34831360, 2021). "Furthermore, the direct impact of LPS and inflammatory cytokines on EPOR was tested in cell lines because of the low EPOR abundance in all organs of CLP sepsis mice." (PMID 34831360, 2021). "The necessity of high-dose EPO is partly due to the LPS-induced EPOR downregulation in sepsis." (PMID 34831360, 2021). "In parallel, EPOR activation downregulated iNOS and IL-1β but increased Arginase-1 and shifted macrophage polarization into an anti-inflammatory stage, to properly balance against sepsis proinflammation." (PMID 34831360, 2021). "The necessity of a high dose of EPO for its anti-inflammatory effect in sepsis might be due to the reduced EPOR in macrophages." (PMID 34831360, 2021). "Despite the detection of EPOR in several immune cells, either innate immunity (macrophages, dendritic cells and mast cells) or adaptive immunity (T cells and B cells), macrophages are important for sepsis immune response, especially in LPS and CLP models." (PMID 34831360, 2021). "In addition, our findings provide indirect evidence that EpoR activation plays a role in sepsis-mediated inflammation." (PMID 22235348, 2012). "Despite the discrepancy between increased hepatocyte-EPOR and reduced macrophage-EPOR, the total expression of EPOR in livers of sepsis mice, a combination of hepatocytes and macrophages (Kupffer’s cells) in liver, was lower than the control group, supporting a possibly too-low EPOR during sepsis." (PMID 34831360, 2021). "Although LPS and inflammatory cytokines enhanced EPOR in hepatocytes in our in vitro data, the decreased viable hepatocytes due to sepsis-induced hepatocyte apoptosis and the increased inflammatory macrophages in livers during sepsis might be responsible to the lower total EPOR in sepsis livers." (PMID 34831360, 2021). "As such, increased endogenous EPO was demonstrated in all sepsis models, including BiNx-CLP despite the reduced liver erythropoietin receptor (EPOR), using Western blot analysis and gene expression, in liver (partly through hepatocyte apoptosis)." (PMID 34831360, 2021).
Sepsis (continued). "In hepatocytes, both LPS and inflammatory cytokines increased EPOR, perhaps trying to increase hepatic EPO production during sepsis for counteracting against hypotension and/or hepatocyte apoptosis." (PMID 34831360, 2021). "In sepsis, the inflammatory cytokines could induce RBC damage, steady-state distribution of iron, downregulation of erythropoietin receptor and bone marrow suppression, which eventually lead to the RDW elevation." (PMID 34254030, 2021). "Despite a non-difference on EPOR expression in kidneys between sepsis and control mice here, an impact of EPOR is beneficial for renal tubular cell protective effect, which might be different from macrophages and hepatocytes." (PMID 34831360, 2021).
diabetic kidney disease (4 papers, 2017 to 2024). Progressive kidney disorder caused by vascular damage to the glomerular capillaries, in patients with diabetes mellitus. "Menne J and colleagues demonstrated that the protective effects of continuous erythropoietin receptor activator (CERA) in diabetic nephropathy were lost when the dose was increased to an extent of elevating Hct level." (PMID 28272424, 2017).
diabetic retinopathy (4 papers, 2009 to 2021). "For this reason mRNA in situ hybridization experiments were performed to identify cellular EPOR expression in the human diabetic retinopathy eye." (PMID 19930719, 2009). "Although absent from in human photoreceptors under normal conditions, our results suggest that EPOR is upregulated in photoreceptors during diabetic retinopathy." (PMID 19930719, 2009). "Recent evidence suggests erythropoietin (EPO) and the erythropoietin receptor (EPOR) may play a direct role in the pathogenesis of diabetic retinopathy." (PMID 19930719, 2009). "Under conditions of ischemia such as diabetic retinopathy, there may be up-regulation of EPOR expression in the photoreceptors and in the peripheral retina." (PMID 19930719, 2009). "Under conditions of diabetic retinopathy, EPOR expression shifted to photoreceptor cells." (PMID 19930719, 2009). "EPOR expression may be a biomarker or contribute to disease mechanisms in diabetic retinopathy." (PMID 19930719, 2009).
head and neck cancer (4 papers, 2007 to 2025). A primary or metastatic malignant neoplasm affecting the head and neck. "EPOR is highly expressed in the tumor cells of head and neck cancer, particularly in the hypoxic and infiltrating areas." (PMID 22639817, 2012).
iron deficiency (4 papers, 2014 to 2021). "Third, iron deficiency reduces the expression of EPOR through interactions with TFR2 and Scribble, a scaffold protein that facilitates EPOR recycling." (PMID 32983414, 2020). "Of note, EPO impacts on iron delivery for erythroid progenitors by stimulating TFR1 mediated iron uptake, whereas iron deficiency (ID) results in reduced expression of the erythropoietin receptor (EPOR) component SCRIBBLE and thus in reduced in EPO signaling in erythroblasts." (PMID 34835988, 2021). "We therefore examined whether iron deficiency might account for the abnormal differentiation of Bcl-xL-Epor−/− erythroblasts, by co-transducing Epor−/− progenitors with Tfrc, in addition to either Bcl-xL or EpoR." (PMID 34921133, 2021). "TFR2 in the bone marrow might be a sensor of iron deficiency that protects against excessive microcytosis in a way that involves EPOR, although the mechanisms remain to be worked out." (PMID 24847265, 2014).
osteosarcoma (4 papers, 2020 to 2025). A usually aggressive malignant bone-forming mesenchymal neoplasm, predominantly affecting adolescents and young adults. "Our results further emphasized that CD163+EPOR+ TAMs are associated with the progression of osteosarcoma lung metastasis." (PMID 32908942, 2020). "Our data demonstrated that the increased percentage of CD163+EPOR+ TAMs was associated with a poor prognosis for osteosarcoma lung metastasis patients." (PMID 32908942, 2020). "Univariate analyses proposed that a ≥2.5-fold increase in the percentage of CD163+EPOR+ TAMs was significantly associated with decreased mDFS and mOS in osteosarcoma lung metastasis patients." (PMID 32908942, 2020). "This study showed that >2.5-fold percentage of CD163+EPOR+ TAMs in osteosarcoma tissues had a significant impact on osteosarcoma prognosis." (PMID 32908942, 2020). "We have characterized TAMs expressing EPOR and CD163+EPOR+ macrophages as TAMs in osteosarcoma lung metastasis patients, which are highly associated with tumor aggressiveness." (PMID 32908942, 2020). "Collectively, our data implied that the percentage of CD163+EPOR+ TAMs was a potential significant prognostic factor in patients with osteosarcomas." (PMID 32908942, 2020). "In conclusion, we have identified and characterized CD163+EPOR+ macrophages as TAMs in osteosarcoma lung metastasis patients." (PMID 32908942, 2020). "Little is known, however, about the expression of EPOR on TAMs and the identity of CD163+EPOR+ TAMs in osteosarcoma lung metastasis has yet to be fully explored." (PMID 32908942, 2020). "In conclusion, our study suggests that TAMs in osteosarcoma lung metastasis samples express EPOR and CD163+EPOR+ macrophages are true TAMs that can promote the progression of osteosarcoma lung metastasis under EPO stimulation." (PMID 32908942, 2020). "We first analyzed the expression profiles of CD163+EPOR+ TAMs in osteosarcoma and para-osteosarcoma tissues." (PMID 32908942, 2020). "Then, we showed that CD163+EPOR+ macrophages in osteosarcoma lung metastasis specimens are TAMs that have developed a distinctive effect in supporting the progression of osteosarcoma lung metastasis." (PMID 32908942, 2020). "We further examined the clinical prognosis of the percentage of CD163+EPOR+ TAMs in the 106 patients with osteosarcoma lung metastases." (PMID 32908942, 2020). "A subpopulation of CD163+ macrophages expresses EPOR in human osteosarcoma lung metastasis specimens." (PMID 32908942, 2020). "Flow cytometry, RT-PCR, and Western blot were examined to define the identity of EPOR+ TAMs in 106 osteosarcoma lung metastasis specimens." (PMID 32908942, 2020). "We also showed that CD163+EPOR+ TAMs were increased 2.5-fold in human osteosarcoma lung metastasis samples." (PMID 32908942, 2020). "Furthermore, CD163+EPOR+ TAMs had higher M2 marker and cytokine expression in osteosarcoma tissues compared with para-osteosarcoma tissues." (PMID 32908942, 2020). "We quantified the relative percentage of CD163+EPOR+ TAMs in osteosarcoma lung metastasis tissues." (PMID 32908942, 2020). "Our findings show that M2 cytokines were highly expressed by CD163+EPOR+ TAMs in osteosarcoma lung metastasis tissues suggested the possibility that CD163+EPOR+ TAMs enhanced the progression of osteosarcoma lung metastasis patients by secreting many different M2 cytokines." (PMID 32908942, 2020). "CD163+EPOR+ macrophages were shown to be true TAMs in osteosarcoma lung metastasis specimens." (PMID 32908942, 2020). "We tested this hypothesis using EPOR-eGFPcre knock in mice and human osteosarcoma lung metastasis samples in vivo and in vitro." (PMID 32908942, 2020). "We hypothesized that TAMs express EPOR, which is a main component of TAMs, and EPO enhances the protumor functions of EPOR+ macrophages to promote the progression of osteosarcoma lung metastasis." (PMID 32908942, 2020).
osteosarcoma (continued). "To further analyze the characterization of CD163+EPOR+ TAMs in osteosarcomas, we determined M2 cytokine expression of sorted CD163+EPOR+ TAMs in osteosarcoma and para-osteosarcoma tissues." (PMID 32908942, 2020). "CD163+EPOR+TAMs increase 2.5 times in human osteosarcoma lung metastasis tissues; CD206, CD163, and PD1, which are known to have a significant role in TAM function had high expression in CD163+EPOR+ TAMs compared with CD163+EPOR− TAMs." (PMID 32908942, 2020). "Clinically, our results reinforce the paradigm that M1-biased macrophage signatures are associated with favorable prognosis, whereas high burdens of M2/TAM subsets (e.g. CD163+ or EPOR+CD163+ TAMs) predict aggressive disease and metastatic potential in osteosarcoma patients." (PMID 41346635, 2025). "In human osteosarcoma lung metastasis specimens, a subpopulation of CD163+ macrophages was found to express erythropoietin receptor (EPOR), CD206, CD163, and PD1, which are known to play significant roles in TAMs immune suppressive and tumor-promoting functions." (PMID 38927907, 2024). "In the future, RNA-seq analyses of CD163+EPOR+ TAMs may help us to better understand of this subset of TAMs, and targeting TAM therapy may be a potential therapeutic intervention in osteosarcoma lung metastasis patients." (PMID 32908942, 2020). "Taken together, we demonstrated that TAMs in osteosarcoma lung metastasis specimens were characterized by the expression of EPOR, suggesting that EPO may play a pivotal role not previously illustrated." (PMID 32908942, 2020). "Having shown that the percentage of CD163+EPOR+ macrophages was increased in osteosarcoma lung metastasis specimens, we examined the expression profiles of these molecules on CD163+EPOR+ and CD163+EPOR− macrophages in osteosarcoma lung metastasis tissues by flow cytometry." (PMID 32908942, 2020).
prostate carcinoma (4 papers, 2013 to 2022). A carcinoma that arises from epithelial cells of the prostate gland. "STAT5 phosphorylation in prostate cancers can be mediated by JAK2 as well as the Erythropoietin receptor (EpoR) for STAT5b." (PMID 32872372, 2020). "The EPOR expression score was significantly elevated in lung (p = 0.011), lymphoma (p = 0.007), thyroid (p = 0.032), uterine (p = 0.038), and prostate cancers (p = 0.011)." (PMID 24004818, 2013). "Furthermore, EPOR expression score was significantly elevated in lung (p = 0.011), lymphoma (p = 0.007), thyroid (p = 0.032), uterine (p = 0.038) and prostate cancers (p = 0.011), however it was not elevated in RCC (p = 0.17)." (PMID 24004818, 2013).
renal cell carcinoma (4 papers, 2012 to 2016). "A previous study demonstrated that EpoR was expressed in kidney tissues removed by nephrectomy or in renal cell carcinoma (RCC) cell lines, and that the proliferation rate of these cells increased with the addition of Epo in a dose-dependent manner." (PMID 23833638, 2013). "Co-expression of erythropoietin (Epo) and erythropoietin receptor (EpoR) has been found in various non-hematopoietic cancers including hereditary and sporadic renal cell carcinomas (RCC), but the Epo/EpoR autocrine and paracrine mechanisms in tumor progression have not yet been identified." (PMID 23028796, 2012).
status epilepticus (4 papers, 2012 to 2023). Status epilepticus is defined as a continuous seizure lasting more than 30 min, or two or more seizures without full recovery of consciousness between any of them. "In animal studies with status epilepticus, several endogenous protective mechanisms to lessen neuronal damage were proposed, including activation ERK1/2, epileptic tolerance, vascular endothelial growth factor, activation of adenosine A1 receptors, erythropoietin receptor." (PMID 22849356, 2012).
acute myeloid leukemia (3 papers, 2018 to 2023). Acute myeloid leukemia (AML) is a group of neoplasms arising from precursor cells committed to the myeloid cell-line differentiation. "The CCLE database (n = 765) showed the expression of EPOR in 23 tumor cell lines, which was the highest in acute myeloid leukemia (LAML) cell lines, the lowest in HNSC cell lines, the highest in the MOLM.16 cell line of LAML, and the lowest in the HCC1187 cell line of BRCA." (PMID 35359375, 2022).
brain infarct (3 papers, 2013 to 2024). "Significant activation of EPOR/βCR double‐positive cells was observed in the peripheral area of the brain infarction 1 day after MCAO surgery." (PMID 38488446, 2024). "Although this study did not investigate the direct interaction between the two receptors, our data indicated that EPOR and βCR could colocate in the same cytoplasm in the peripheral area of brain infarction following a cerebral ischemic insult." (PMID 38488446, 2024).